ANXA2 (annexin A2)
Diseases named in the same sentence as ANXA2 in open-access papers (continued):
Sharing a sentence is not in itself a finding about the gene and the disease.
lung carcinoma (continued). "Previous studies provided evidence that in patients with lung cancer, a poor prognosis for survival is correlated with Annexin A2 expression, and this observation is consistent with the results of Annexin A2 tissue staining in lung cancer." (PMID 28886730, 2017). "This SCG label-free lung cancer biosensor showed to have the lower detection limits ever reported for the three different tumors markers ANXA2, VEGF, and ENO1." (PMID 26805845, 2016). "After the immobilization process of the antibodies, the label-free suspended SCG sensor was ready for detection of the important lung cancer biomarkers: ANXA2, VEGF, and ENO1." (PMID 26805845, 2016). "The over-expression or post-translational modification of annexin A2 has been reported in various cancers, such as colorectal, oral and lung cancers." (PMID 26774260, 2016). "We confirmed that ANXA2 was correlated with therapeutic resistance, and consistent result was also reported in lung cancer." (PMID 26196246, 2015). "In one study, the presence of ANXA2 autoantibody in sera can be detected in lung cancer patients with squamous cell carcinoma (33%) and lung adenocarcinoma (60%)." (PMID 24591759, 2014). "The same study found that the generation of anti-ANXA2 antibodies is correlated with the serum levels of IL-6 in lung cancer patients." (PMID 24591759, 2014). "Tumor growth of fibrosarcoma (HT1080) and lung cancer (A459) cell lines in NOD-SCID mice has also been shown to be inhibited following annexin A2 depletion." (PMID 23945256, 2013). "Therefore, TIM-4 promotes mitochondrial function and participates in lung cancer proliferation via ANXA2/PI3K/AKT axis." (PMID 36806050, 2023). "We then investigated whether ANXA2 participates in TIM-4 mediated regulation of mitochondrial function in lung cancer cells." (PMID 36806050, 2023). "It was reported that the survival rate of patients with lung cancer decreased when ANXA2 was up-regulated, which might serve as a potentail biomarker for NSCLC." (PMID 32351780, 2020). "In addition, silencing of AnxA2 in lung cancer stem cells in mice induced a reduction in tumor weight, which correlated with the loss of both β-catenin and S100A100, suggesting that AnxA2 may directly or indirectly regulate metastasis." (PMID 32575495, 2020). "In addition, down-regulation of ANXA2 could attenuate tumor growth and metastasis in lung cancer, which could reduce the size of lung cancer tumor to 19%." (PMID 32351780, 2020). "For example, ANXA2 may promote the progression and invasion of human lung cancer cell." (PMID 31186633, 2019). "Therefore, Annexin A2 could potentially be used as an important therapeutic target in drug-resistant lung cancers." (PMID 28886730, 2017). "In lung cancer cells, IFN‐γ triggered annexin A2 (ANXA2) exocytosis via a Rab11‐Rab8a and Rab27a mediated secretory autophagy pathway including the fusion of AP and MVB to form amphisome followed by migration to the plasmid membrane and exocytosis." (PMID 38804615, 2024). "ANXA2 interacted with T-cell immunoglobulin and mucin domain-containing molecule 4 (TIM-4) and mediated TIM-4-induced lung cancer progression by activating PI3K/AKT/OPA1 axis." (PMID 38688909, 2024). "Some of these proteins, such as Annexin A2 and S100A9, are involved in regulation of immune escape in some cancer types, including lung cancer." (PMID 33546102, 2021). "CD147 and Annexin A2 were distributed in membrane and cytoplasm in three HCC cell lines and lung cancer A549 cells." (PMID 26716413, 2016). "Additionally, researchers have found that TIM-4 interacts with ANXA2 to activate the PI3 K/AKT signaling pathway, promoting oxidative phosphorylation in lung cancer cells to accelerate tumor progression." (PMID 40481236, 2025).
lung carcinoma (continued). "For example, CAFs can over‐secret ANXA2, which triggers EMT in lung cancer cells; this pro‐EMT phenotype is dependent on the secretion of hepatocyte growth factor (HGF) and insulin‐like growth factor 1 (IGF1) by CAFs, thus facilitating the cancer cells' evasion of EGFR targeting." (PMID 40162549, 2025). "The displacement of S100A10 from annexin A2 by DLC1, a Rho GTPase-activating protein (RhoGAP) that functions as a tumor suppressor, results in the attenuation of plasminogen activation and impaired invasion of A549 lung cancer cells." (PMID 30572596, 2018). "In peripheral blood, the ANXA2 serum level has been evaluated in patients with HCC (median, 69.6 ng/ml), early-stage HCC (median, 150 ng/ml), gastric cancer (median, 211.0 ng/ml), lung cancer, and oral squamous cell carcinoma (median, 27.1 ng/ml)." (PMID 29598816, 2018). "IRF1 is downregulated in lung cancer, IPF and PAH datasets, probably because it represses the expression of genes involved in anti-proliferative response, such as BIRC5/survivin, CCNB1, CCNE1, CDK1, CDK2 and CDK4 and in immune response, such as FOXP3, IL4, ANXA2 and TLR4." (PMID 31867044, 2019). "In nonsmall cell lung cancer (NSCLC), A549-derived tumors, ANXA2 is highly expressed near proliferative cells but not in either the necrotic region or in apoptotic cells." (PMID 24591759, 2014).
gastric cancer (46 papers, 2007 to 2026). A primary or metastatic malignant neoplasm involving the stomach. "ANXA1 and ANXA2 were selected, since they are described to play a role in gastric cancer and ANXA2 was found to be up-regulated in H. pylori-associated gastric cancer." (PMID 35176125, 2022). "There is a clinical association between upregulated ANXA2 and tumorigenesis in gastric carcinoma." (PMID 24591759, 2014). "Annexin A2 (ANXA2) promotes the progression of several cancers, including oesophageal, pancreatic, and gastric cancers." (PMID 40069750, 2025). "First, we confirmed that FBXW10 can form a complex with ANXA2 and mediate K63 ubiquitination of ANXA2 in gastric cancer." (PMID 41185558, 2025). "Li et al21 elaborated that S100A10 is markedly upregulated in gastric cancer and activates the mTOR pathway by interacting with annexin A2 to accelerate tumor glycolysis, thereby promoting malignant cell proliferation while suppressing apoptosis." (PMID 39128058, 2024). "Silencing SLP-2 can inhibit gastric cancer cell proliferation and induce apoptosis and autophagy via ANXA2/ β-catenin signal pathway." (PMID 36788223, 2023). "The downregulation of ANXA2 stalls cells in the G1 phase or S-G2/M phase in gastric cancer and glioblastoma multiforme, respectively." (PMID 36936694, 2023). "Some evidence indicated that Annexin A2 is involved in the interaction between Mycoplasma hyorhinis (M. hyorhinis) and certain tumours, such as gastric cancer and hepatocarcinoma." (PMID 37482693, 2023). "MiR-101 is also discovered being an ANXA2-targeted molecule and have capability of down-regulating expression of ANXA2 in drug-resistant gastric cancer." (PMID 33995636, 2021). "Among them, ANXA2 was found from interactions of the HpaA in two gastric cancer cell lines with the highest score and more unique peptides according to the results of HPLC-MS/MS." (PMID 32566649, 2020). "Accumulated evidence has indicated that ANXA2 expressed on the cell membrane of gastric cancer cells was important to maintain the malignancy of cells and becomes a potential prognostic marker in gastric cancer." (PMID 32566649, 2020). "We investigated the effect of a lentivirus-mediated knock-down of ANXA2 on the proliferation, invasion and migration of gastric cancer AGS cells." (PMID 31186633, 2019). "Summarizing other studies, ANXA2 was upregulated in gastric cancer tissues and as a direct target of miR-101, miR-101 alleviated chemoresistance of cisplatin or vincristine in gastric cancer cells by targeting ANXA2." (PMID 29291003, 2017). "It has also been reported that, in 133 of 436 gastric cancer cases, the ANXA2 expression is elevated in gastric cancer tissues compared with noncancerous tissues." (PMID 24591759, 2014). "A recent study using a proteomic approach investigating the secretome of the gastric cancer cell line SGC7901 identified annexin A2 as a secreted phosphoprotein." (PMID 22681645, 2012). "Also, ANXA2 promoted gastric cancer cell invasion and metastasis through the EphA2-YES1-ANXA2 signaling pathway." (PMID 36713082, 2023). "Additionally, it is demonstrated that S100A10 promotes the malignant growth of cancer cells by activating the AKT/mTOR signaling pathway in osteosarcoma and the Src/ANXA2/AKT/mTOR signaling pathway in gastric cancer." (PMID 36612197, 2022). "When ANXA2 is silenced, the ability of proliferation, invasion, and migration of gastric cancer cells is weakened, but when it is overexpressed, it can promote the migration, invasion, and metastasis of esophageal cancer cells in vitro and in vivo by activating the MYC-HIF1a-VEGF cascade pathway." (PMID 35280928, 2021). "In another 436 gastric cancer cases, 133 gastric cancer tissue display upregulation of ANXA2." (PMID 33995636, 2021). "In addition, miR-23b-3p and miR-101 are able to reverse drug resistance of gastric cancer cells to multiple chemotherapeutics including VCR via targeting ATG12/HMGB2 as well as ANXA2." (PMID 32192494, 2020).
gastric cancer (continued). "In addition, another annexins family member, ANXA2, has also been observed to be overexpressed in gastric cancer and is related to poor clinical outcome, making it a potential prognostic factor." (PMID 22970268, 2012). "Therefore, the over-expression of ANXA2 in colorectal and gastric carcinomas alludes to a correlation with invasiveness and poor prognosis and is in line with our analysis." (PMID 22040021, 2011). "ANXA2 was overexpressed in advanced gastric carcinomas and could have contributed to its progression." (PMID 17927838, 2007). "This phosphorylation event activates ANXA2 and leads to increased nuclear distribution of ANXA2 in gastric cancer (GC) cells." (PMID 40234383, 2025). "Here, we show that EphA2, YES1, and ANXA2 form a signal axis, in which YES1 activated by EphA2 phosphorylates ANXA2 at Tyr24 site, leading to ANXA2 activation and increased ANXA2 nuclear distribution in gastric cancer (GC) cells." (PMID 33941853, 2021). "Furthermore, ANXA2 has been shown to correlate with gastric cancer growth and spreading, suggesting a role in metastasis; a similar role for ANXA2 could be envisaged in the establishment of endometriotic lesions." (PMID 32106990, 2020). "For instance, ANXA2 directs the interaction of the protein YES1 and involves the EphA2-YES1-ANXA2 pathway, which promotes gastric cancer progression and metastasis, while ANXA6 suppresses gastric cancer progression by inhibiting Ras/MAPK signalling." (PMID 36936694, 2023). "ANXA2 interacts with S100A10 in gastric cancer to activate the mTOR pathway and inhibit apoptosis in gastric cancer cells." (PMID 37420211, 2023). "Accordingly, in gastric cancer HGC-27 cells, the inhibition of ANXA2 was found to significantly reduce the migration and secretion of MMPs and inhibit cancer invasion and metastasis." (PMID 36936694, 2023). "The MYOF, CLIP1, AHNAK, ANXA2, ITPRIPL2 and LEPROT genes in tissues of patients with gastric cancer were found to be altered by amplification, extensive deletion, truncating mutations, splice mutations, missense mutations, and high/low mRNA expression." (PMID 36147922, 2022). "By modulating Annexin A2 (ANXA2) and VEGF-C expression, tumor suppressor miR-101 has been found to reverse DDP resistance of gastric cancer cells." (PMID 32192494, 2020). "However, the biological behavior of ANXA2 in gastric cancer (GC) remains unclear." (PMID 31186633, 2019). "The N-terminal region of recombinant p37 binds to ANXA2 and the p37-23 peptide blocks M. hyorhinis infection of MGC803 and AGS human gastric cancer cells." (PMID 26512722, 2015). "In addition, it has been demonstrated that EphA2 activates ANXA2 by phosphorylating the Tyr426 site of YES1, which in turn promotes the proliferation, migration and invasion of gastric cancer cells." (PMID 39050762, 2024). "Similarly, YES1 phosphorylates ANXA2 on Tyr24, which drives gastric cancer invasion and metastasis by the activation of EphA2/YES1/ANXA2 axis." (PMID 36247003, 2022). "Interestingly, we have found decreased phosphorylation of ANXA2 at Y715 and a decrease in phosphorylation of STAT3 upon inhibition of CAMKK2 in gastric cancer cells." (PMID 35646067, 2022). "ANXA2 expression increases in tumors with lymph node metastasis as compared to non-neoplastic gastric cancer cells." (PMID 32099594, 2019). "Herein, we synthesized the N-terminal of ANXA2 polypeptide (A2PP) and found that A2PP could decrease the infection of M. hyorhinis to gastric cancer cells and block M. hyorhinis infection-induced cell migration." (PMID 26812398, 2016). "However, the functional significance of ANXA2 overexpression in gastric cancer has not been investigated." (PMID 24591759, 2014). "In gastric cancer, S100A10 and AHNAK2 are common DEGs that might be involved in Salmonella infection; however, annexin A2 is not, suggesting that the pathway might be actin independent or another protein is recruited to actin assembly sites at cellular membranes." (PMID 39228892, 2024).
colorectal cancer (45 papers, 2009 to 2025). A primary or metastatic malignant neoplasm that affects the colon or rectum. "Previous studies have shown that ANXA2 overexpression is strongly associated with the progression of multiple malignancies, and promotes the metastatic potential of endometrial cancer, kidney cancer and colorectal cancer." (PMID 35371986, 2022). "MIR155HG promotes M2 macrophage polarization and tumor progression and enhances oxaliplatin resistance in colorectal cancer cells via the miR-650/ANXA2 axis." (PMID 38339237, 2024). "Another group found that cancer-associated fibroblast (CAF)-derived exosome LINC00659 promotes colorectal cancer cell proliferation, invasion, and migration through the miR-342-3p / ANXA2 axis." (PMID 38558328, 2024). "miR-155 modified the miR-650/ANXA2 axis and enhanced colorectal cancer advancement and resistance of oxaliplatin through M2 macrophage polarization in colorectal cancer cells." (PMID 36430305, 2022). "miR-155 and Annexin A2 (ANXA2) are vastly involved in colorectal cancer tissues/cells and analytically have prognostic standards for colorectal patients." (PMID 36430305, 2022). "Recently, accumulated studies suggest that ANXA2 is involved in the metastasis of several types of cancer, including gastric cancer, colorectal cancer, prostate cancer, and breast cancer." (PMID 35977942, 2022). "For example, in colorectal cancer (CRC), LINC00460 increases and adjusts the expression of ANXA2, which is associated with the expression of E-cadherin and N-cadherin, which promote cell invasion and EMT." (PMID 34540695, 2021). "In colorectal cancer, upregulation of AnxA2 is regulated by TGF-β, which induces epithelial–mesenchymal transition." (PMID 32575495, 2020). "In 105 cases of primary colorectal carcinoma tissues, ANXA2 is overexpressed in the cancer cell membrane of the carcinoma cells more than in tumor stroma fibrous tissue, the muscularis propria, the vessel wall, and the adjacent normal bowel wall." (PMID 24591759, 2014). "In 150 pairs of colorectal carcinoma tissue and the corresponding adjacent normal tissue, ANXA2 is mainly located in the plasma membrane, and dramatically upregulated in tumor cells compared with normal tissue." (PMID 24591759, 2014). "Tissue microarrays and proteome analysis showed that up-regulated annexin A2 expression also predicted higher lymph node metastasis (LNM) in colorectal cancer patients." (PMID 23519104, 2013). "Annexin A2 is up-regulated in 29.5% of colorectal cancer patient samples and this up-regulation correlated with tumor size, advanced histology, and depth of invasion and pTNM stage (pathological tumor-node-metastasis)." (PMID 23519104, 2013). "It has also been recently described an ANXA2-targeting peptide motif CBP12 with highly selectivity and affinity to ANXA2 and proved ability to specifically target colorectal cancer cells, therefore emerging as a candidate for ANXA2-targeted therapeutic strategies." (PMID 36247003, 2022). "Moreover, a previous report indicates that lncRNA MIR155HG participates in the regulation of ANXA2 and induces M2 macrophage polarization and drug resistance of colorectal cancer." (PMID 35977942, 2022). "Consistently, Anxa2 associates with STAT3 and confers the aggressive behavior in colorectal cancer." (PMID 31113450, 2019). "Annexin A2 (ANXA2) is upregulated in several malignancies, including colorectal cancer (CRC)." (PMID 30050103, 2018). "Though ANXA2 had high mRNA expression in one population of human colorectal tumors, it is downregulated in some populations of human prostate tumors and colorectal cancer cell lines." (PMID 20824133, 2010). "Indeed, ANXA2 overexpression promotes colorectal cancer invasiveness through the STAT3 pathway and may regulate the proliferation, invasion and migration of colorectal cells through the same pathway." (PMID 36916296, 2023).
colorectal cancer (continued). "ANXA2 was reported to activate AKT/GSK3β and AKT/mTOR signaling in gastric, breast, and colorectal cancer, whereas ANXA2 is a substrate of ITSN1-L-mediated cell–substrate adhesion through the FAK/integrin β3 pathway." (PMID 35977942, 2022). "TRIM65 accelerates colorectal cancer metastasis by targeted degradation of ARHGAP35 protein, promotes the invasion of endometrial stromal cells through DUSP6 ubiquitination, activates ERK1/2/C-myc signals, and promotes bladder cancer cells through ubiquitination and degradation of ANXA2 invasion." (PMID 36035221, 2022). "The remaining investigated CSC markers (DCLK1, ANXA2, and CD44) did not demonstrate a statistically significant relationship with tested clinicopathological features of colorectal cancer." (PMID 32671503, 2020).